PON2 (paraoxonase 2)
Diseases named in the same sentence as PON2 in open-access papers (continued):
Sharing a sentence is not in itself a finding about the gene and the disease.
Cognitive impairment (1 paper, 2022). Abnormal cognition is characterized by deficits in thinking, reasoning, or remembering. "Male rats seemed to be more vulnerable than female rats to hippocampal injury and cognitive impairment induced by CHH, possibly due to the low expression level of PON2 protein in males." (PMID 36003965, 2022).
cystic fibrosis (1 paper, 2012). Autosomal recessive disorder caused by pathogenic variants in the CFTR gene (cystic fibrosis transmembrane conductance regulator), which encodes a chloride and bicarbonate channel expressed in epithelial cells, and follow the diagnosis criteria. "Because 3OC12HSL is detected in lungs of cystic fibrosis patients infected with P. aeruginosa, we investigated the relationship between P. aeruginosa infection and gene expression of PPARγ and PON2 in bronchoalveolar lavage fluid (BALF) of children with CF." (PMID 22860094, 2012).
endometriosis (1 paper, 2025). The growth of functional endometrial tissue in anatomic sites outside the uterine body. "Another enriched pathway across the four conditions is ‘arachidonic acid metabolism’; of the five endometriosis genes enriched in this pathway, four are shared with the other three immune conditions, namely, DPEP3, GPX1, DPEP2, and PON2." (PMID 40262193, 2025).
fatty liver (1 paper, 2022). "To investigate whether hepatic steatosis affects PON2 expression and activity, we used in vitro fatty liver model that induces lipid accumulation in L02 normal liver cells via PA treatment." (PMID 36509805, 2022).
gram-negative bacterial infections (1 paper, 2025). Infections caused by bacteria that show up as pink (negative) when treated by the gram-staining method. "The PON-2 enzyme is located on the plasma membrane, and in vitro studies have shown that its lactonase activity and pro-apoptotic function contribute to defense against Gram-negative bacterial infections by regulating biofilm formation and the production of virulence factors." (PMID 40002395, 2025).
head and neck squamous cell carcinoma (1 paper, 2025). A squamous cell carcinoma that arises from any of the following anatomic sites: lip and oral cavity, nasal cavity, paranasal sinuses, pharynx, larynx, and salivary glands. "Biomarkers such as HPV DNA/mRNA, HPV-E6, EBV RNA, p16^Ink4a, and the more recently identified NNMT and PON2 play critical roles in the diagnosis, prognosis, and prediction of treatment response in head and neck squamous cell carcinoma (HNSCC)." (PMID 40864763, 2025).
Hyperglycemia (1 paper, 2015). An increased concentration of glucose in the blood. "Patients with a strongly YZ constitution may have PON2 polymorphism with a low protein function which tends to decrease its antioxidative efficacy, resulting in cardiovascular disturbance and hyperglycemia." (PMID 26169365, 2015).
Impaired glucose tolerance (1 paper, 2019). An abnormal resistance to glucose, i.e., a reduction in the ability to maintain glucose levels in the blood stream within normal limits following oral or intravenous administration of glucose. "Our study demonstrated that PON2 deficiency leads to increased DIO and impaired glucose tolerance in mice." (PMID 30641857, 2019).
lupus nephritis (1 paper, 2011). Glomerulonephritis in the context of systemic lupus erythematosus. "Three PON2 tagSNPs (rs11981433, rs17876183, and rs17876205) showed modest association with lupus nephritis (age and recruitment site adjusted p-values ranging between 0.013-0.032)." (PMID 21223581, 2011). "Similarly, we observed modest associations of PON2 SNPs with lupus nephritis in Caucasian SLE cases (rs11981433, rs17876183 and 17876205 with covariate-adjusted p-values ranging between 0.013-0.032)." (PMID 21223581, 2011). "Our data indicate that PON2 genetic variants significantly affect variation in serum PON activity and have modest effects on risk of lupus nephritis and SLE-related immunologic disorder." (PMID 21223581, 2011).
nephritis (1 paper, 2011). Inflammation of renal tissue. "Our pairwise LD analysis of the nephritis-associated three PON1 promoter SNPs (rs705379, rs705381 and rs854573) and three PON2 SNPs did not reveal high correlations between these SNPs (data not shown)." (PMID 21223581, 2011).
neuroblastoma (1 paper, 2025). Neuroblastoma (NB) is the most common solid, extracranial childhood tumor. "PA and CPF exposure have been observed to elevate the production of ROS in neuroblastoma cells, however, PA has been also found to elevate PON2 levels which ensure proper oxidative stress regulation." (PMID 40794328, 2025). "For example, chlorpyrifos and parathion increased ROS levels in neuroblastoma cells, though parathion simultaneously elevated PON2 expression, suggesting a compensatory mechanism." (PMID 40794328, 2025). "Neuroblastoma cell lines treated with chlorpyrifos (CPF) contained low PON2 protein levels while exposure to papthion (PA) enhanced PON2, but minimal paraoxonase activity was seen." (PMID 40794328, 2025).
non-small cell lung carcinoma (1 paper, 2016). A group of at least three distinct histological types of lung cancer, including non-small cell squamous cell carcinoma, adenocarcinoma, and large cell carcinoma. "Importantly, PON2 expression is markedly elevated in several human non-small cell lung carcinoma (NSCLC) cell lines, which is associated with resistance to classical anticancer drugs like doxorubicin or cisplatin." (PMID 26758417, 2016).
ovarian tumor (1 paper, 2018). "Taken together, we report for the first time that PON2 acts as a tumor suppressor in the early stage of OC by reducing IGF-1 production and its signaling, indicating PON2 activation might be a fruitful strategy to inhibit early stage ovarian tumor." (PMID 29531225, 2018). "Altogether, our study demonstrated for the first time that PON2 inhibits ovarian tumor growth." (PMID 29531225, 2018).
renal carcinoma (1 paper, 2025). A carcinoma arising from the epithelium of the renal parenchyma or the renal pelvis. "In renal carcinoma, PON2 knockdown enhanced apoptosis by reducing Ki-67 expression and activating caspase-3." (PMID 40794328, 2025).
renal cell carcinoma (1 paper, 2025). "PON2 suppression in renal cell carcinoma cells was found to be contributing to apoptosis by lowering Ki-67 expression and increasing caspase-3 activation." (PMID 40794328, 2025). "PON2 downregulation in renal cell carcinoma triggered a drop in cell viability, which became more apparent after CDDP and 5-FU treatment." (PMID 40794328, 2025). "PON2 downregulation in renal cell cancer cells impaired antioxidant defences reflected by elevated ROS levels upon CDDP and 5-FU treatment." (PMID 40794328, 2025).
renal dysfunction (1 paper, 2011). "A large prospective study comprising 3,374 diabetic subjects evaluated PON2 variations with indices of renal dysfunction and reported the association of PON2/rs6954345 (p.Ser311Cys) and rs12704795 SNPs with renal dysfunction." (PMID 21223581, 2011).
retinal diseases (1 paper, 2023). "However, a deeper understanding of the signaling pathways of PON2 action needs to be pursued, and ways to elevate PON2 levels as a possible treatment for AMD or other retinal diseases may prove to be a valuable approach." (PMID 37891899, 2023).
sickle cell disease (1 paper, 2019). Sickle cell anemias are chronic hemolytic diseases that may induce three types of acute accidents: severe anemia, severe bacterial infections, and ischemic vasoocclusive accidents (VOA) caused by sickle-shaped red blood cells obstructing small blood vessels and capillaries. "Here, for the first time, the arylesterase and paraoxonase activities of PON-1 were evaluated, as well as the frequency of the polymorphism in PON-1, PON-2, and PON-3 genes, in patients with sickle cell disease." (PMID 31366068, 2019). "The allele distribution of the PON-1, PON-2, and PON-3 polymorphisms followed the Hardy–Weinberg equilibrium in the sickle cell disease group as well as in the healthy control group." (PMID 31366068, 2019). "Here, for the first time, we described PON-1 activities and PON-1, PON-2, PON-3 polymorphisms in patients with sickle cell disease, homozygous for HbSS, compared with healthy controls." (PMID 31366068, 2019).
squamous carcinoma (1 paper, 2025). "A study examining squamous carcinoma cells (SCC) tissue samples showed that tumour tissues had significantly higher levels of PON2 expression than healthy margins, regardless of no discernible correlation with clinical characteristics." (PMID 40794328, 2025).
tumor (39 papers, 2003 to 2025). "Elevated PON2 expression has been associated with enhanced tumor aggressiveness in several malignancies, including colorectal cancer, skin cancer and lung adenocarcinoma." (PMID 41303537, 2025). "Higher PON-2 expression in OSCC has been associated with tumor relapse, regardless the type of treatment." (PMID 31052559, 2019). "The ability of PON3 to restore the sensitivity of PON2-deficient tumor cells to C12 suggests that overlapping enzymatic activities of PON2 and PON3 mediate C12 killing activities." (PMID 26758417, 2016). "Furthermore, PON2 has been implicated in tumor biology, but further in vivo research is necessary to confirm in vitro results." (PMID 41303537, 2025). "Since TNBC is highly aggressive, has limited therapeutic options, and is chemoresistant, further investigation was focused on exploring PON2’s involvement in the molecular mechanisms underlying cell proliferation and sensitivity to drug treatment affecting this tumor form." (PMID 38397445, 2024). "However, the significance of enzyme upregulation, together with the impact on tumor cell phenotype associated with PON2 dysregulation, is far to be completely disclosed." (PMID 36613780, 2022). "In this light, PON2 silencing in BC cells may therefore represent a novel molecular approach to control tumor growth and its susceptibility to chemotherapeutics." (PMID 28430636, 2017). "Elevated PON2 expression correlates with tumour survival, enhanced cell migration, and metastatic potential, often contrasting with its reduced levels in adjacent non-tumour tissues." (PMID 40794328, 2025). "PON2, through its anti-apoptotic and antioxidant activity, appears to support tumor cell survival and resistance to chemotherapy." (PMID 40864763, 2025). "PON2 knockdown in AITL models reduced proliferation and increased apoptosis, whereas tumours deemed PON2-positive showed poorer survival rates." (PMID 40794328, 2025). "Mechanistically, PON2 modulates endoplasmic reticulum stress and mitochondrial superoxide generation, thereby protecting tumour cells from oxidative and apoptotic damage." (PMID 40794328, 2025). "PON2 overexpression was observed in tumour tissues, which was in contrast to adjacent normal tissues, while PON2 expression was steadily decreased using shRNA (short hairpin RNA) in the non-small cell lung cancer (NSCLC) cell lines A549 and NCI-H1299." (PMID 40794328, 2025). "From a diagnostic and prognostic standpoint, large-scale clinical studies are needed to validate PON2 as a biomarker of tumour aggressiveness and treatment response." (PMID 40794328, 2025). "PON2 has emerged as a multifunctional enzyme with profound implications in cancer biology, influencing tumour initiation, progression, therapeutic responsiveness, and resistance." (PMID 40794328, 2025). "Multiple studies have demonstrated that PON2 contributes to tumor growth and metastatic progression." (PMID 41303537, 2025). "The outcomes underscore PON2's complex involvement in cancer biology, spanning tumour initiation, progression, and therapeutic resistance." (PMID 40794328, 2025). "Through its regulation of ROS and oxidative stress, PON2 is a key determinant of cancer cell proliferation, survival, and treatment response across multiple tumor types." (PMID 41303537, 2025). "In the last decade, many studies have extended the analysis of PON2 involvement to other neoplasms, trying to deeply investigate its potential contribution to cancer cell aggressiveness." (PMID 38397445, 2024). "Subsequent studies were performed on the HSC-3 and HOC621 OSCC cell lines, in which PON2 gene silencing was achieved and the impact on tumor cell phenotype was explored." (PMID 38397445, 2024). "The analysis of enzyme expression was also extended to exfoliated urinary cells from subjects with BC and healthy controls, as PON2 mRNA levels are significantly inversely related to the tumor stage." (PMID 38397445, 2024).
tumor (continued). "The data obtained from analyses of tumor cell lines led to the identification of the molecular mechanisms by which PDAC cells are positively affected by PON2 overexpression, thus promoting tumor progression." (PMID 38397445, 2024). "Among gynecologic cancers, PON2 mRNA expression was found to be upregulated in a larger number of tumor tissues compared to their normal counterparts obtained from women with ovarian cancer (OC)." (PMID 38397445, 2024). "This discrepancy suggests an important context dependency for PON2’s role in regulating tumor cell physiology." (PMID 37337025, 2023). "Unfortunately, the protective function of PON can also have negative consequences in certain cases, for example, in some cancer cell lines overexpression of PON2 increases cell resistance to chemotherapeutic agents and decreases tumor cell apoptosis." (PMID 36653584, 2023). "Taken together, these results paint a complicated picture of PON2’s role in tumorigenesis broadly and implicate its diverse roles in different tumor types." (PMID 37337025, 2023). "These reported discrepancies suggest PON2’s influence on tumor growth in vivo likely depends on microenvironmental factors corresponding to distinct organs and tissues that give rise to neoplastic growth." (PMID 37337025, 2023). "The overexpression of PON2 is found in many tumors and often correlates with tumor aggressiveness and poor prognosis." (PMID 36552527, 2022). "From here on scientists explored PON2 antioxidant effects, its role in preventing heart failure and its involvement in any type of tumor." (PMID 33562328, 2021). "Other mechanisms potentially involved in the antiapoptotic role of PON2 in tumor cells include UPR, a signaling pathway triggered during cell stress." (PMID 33562328, 2021). "Due to its intracellular localization, as well as its antioxidant function, PON2 was reported to display an anti-apoptotic role, with potential consequences for tumor cell behavior." (PMID 32093309, 2020). "Overexpression of PON2 led to a significant increase in tumor cell proliferation and resistance to oxidative stress, while silencing of PON2 expression inhibited cancer cell proliferation, migration, and invasion." (PMID 32802843, 2020). "Many research groups have recently focused their interest on exploring the role played by PON2 in tumor cells, and enzyme upregulation was found in oral, bladder, pancreatic, ovarian, and gastric cancer." (PMID 33297311, 2020). "The sum of these considerations strongly support data demonstrating that PON2 overexpression in tumor cells protects against treatment with chemotherapeutic drugs, mainly those acting by induction of the oxidative stress response." (PMID 33297311, 2020). "While the antioxidative effects exerted by PON2 have been described for a long time, only recently this enzyme was reported to be able to modulate execution of the apoptotic program in tumor cells." (PMID 33297311, 2020). "Upregulated levels of PON2 have been detected in different types of cancer cells including BC, and a possible involvement of the role of PON2 higher expression in apoptotic escape of tumor cells has been suggested." (PMID 31191796, 2019). "Bacchetti and collaborators observed significant differences in urine PON2 expression when compared Ta and T1-3 tumours, showing higher expression in tumours confined to the basement membrane than in those invading other histological layers." (PMID 30149597, 2018). "PON2 has been shown to be upregulated in tumor tissues relative to corresponding normal tissues in many types of cancers." (PMID 29531225, 2018). "Using a mouse xenograft model of OC, we demonstrate that overexpression of PON2 prevents tumor formation." (PMID 29531225, 2018). "Our results suggest that PON2 overexpression reduces the tumor forming potential of ID8 cells by reducing the IGF-1 signaling and its signaling pathway." (PMID 29531225, 2018).